SLC17A4 (solute carrier family 17 member 4)
Description:
Acts as a membrane potential-dependent organic anion transporter, the transport requires a low concentration of chloride ions. Mediates chloride-dependent transport of urate. Mediates sodium-independent high affinity transport of thyroid hormones including L-thyroxine (T4) and 3,3',5-triiodo-L-thyronine (T3). Can actively transport inorganic phosphate into cells via Na(+) cotransport.
Synonyms: KIAA2138; KAIA2138
Tractability: Antibody: UniProt places it where antibodies can reach, with high confidence; its Gene Ontology location is reachable by antibodies, with high confidence; UniProt predicts a signal peptide or a membrane-spanning region.
Gene: Protein-coding gene on chromosome 6 (25,753,300 to 25,783,316, forward strand). Ensembl gene ENSG00000146039.
Subcellular location: Apical cell membrane
Gene Ontology:
Molecular function: sodium:phosphate symporter activity; thyroid hormone transmembrane transporter activity; urate transmembrane transporter activity; transmembrane transporter activity
Biological process: sodium-dependent phosphate transport; phosphate-containing compound metabolic process; sodium ion transport; sodium ion transmembrane transport; thyroid hormone transport; transmembrane transport; urate transport
Cellular component: apical plasma membrane; brush border membrane; membrane; plasma membrane
Genetic constraint (gnomAD): Loss-of-function variants: 34 observed, 55.8 expected, observed/expected ratio (o/e) 0.61, 90% interval 0.46 to 0.81. The upper end of that interval is the gene's LOEUF score, 0.81, which puts it in group 3 of 6, group 1 being the genes least tolerant of losing a copy. Missense variants: 584 observed, 627.93 expected, observed/expected ratio (o/e) 0.93, 90% interval 0.87 to 1. Synonymous variants: 225 observed, 228.17 expected, observed/expected ratio (o/e) 0.99, 90% interval 0.88 to 1.1.
Homologues: Orthologues: chimpanzee SLC17A4 (99% identical), macaque SLC17A4 (98% identical), rat Slc17a4 (79% identical), guinea pig SLC17A4 (79% identical), mouse Slc17a4 (78% identical), rabbit SLC17A4 (69% identical), pig SLC17A4 (68% identical), dog SLC17A4 (54% identical), zebrafish si:ch1073-513e17.1 (36% identical), zebrafish slc17a5 (35% identical), Drosophila melanogaster CG6978 (30% identical), Drosophila melanogaster Picot (29% identical), and 45 more. Paralogues in human: SLC17A2 (57% identical), SLC17A3 (52% identical), SLC17A1 (45% identical), SLC17A5 (35% identical), SLC17A8 (33% identical), SLC17A6 (31% identical), SLC17A7 (31% identical), SLC17A9 (21% identical), SLC37A1 (19% identical), SLC37A2 (17% identical), SLC37A4 (16% identical), SLC37A3 (14% identical).
Diseases named in the same sentence as SLC17A4 in open-access papers:
SLC17A4 is named in the same sentence as 12 diseases in open-access papers, as found by Europe PMC text mining. Sharing a sentence is not in itself a finding about the gene and the disease. The quoted sentences say what the papers report.
gout (4 papers, 2017 to 2024). A condition characterized by painful swelling of the joints, which is caused by deposition of urate crystals. "Among the fourteen genes, six genes (ABCG2, SLC2A9, TRIM46, SLC17A1, A1CF and SLC17A4) affected both the elevation of the serum urate level and the development of gout from hyperuricemia and were identified as risk factors for gout." (PMID 28252667, 2017). "In this study, SLC17A4 was found to be associated with both gout and the development of gout from hyperuricemia, which partially explains the mechanism of the progression from hyperuricemia to gout." (PMID 28252667, 2017). "After multiple correction, except for the genes PDZK1 and SLC17A4, the remaining ten genes still had effects on the risk of gout with a PFDR value less than 0.05." (PMID 28252667, 2017). "After multiple correction, the association between two genes, ABCG2 and SLC17A4 (novel gout-associated gene), remained significant (OR = 1.56, PFDR = 3.68E-09; OR = 1.27, PFDR = 0.013, respectively)." (PMID 28252667, 2017). "As a result, SLC17A4 was found to be a novel gout-associated gene affecting the risk of gout (OR = 1.19, PFDR = 0.018)." (PMID 28252667, 2017). "Consequently, another novel gout-associated gene, SLC17A4, was identified as a risk factor for the pathogenesis of gout in males (OR = 1.19, PFDR = 0.035)." (PMID 28252667, 2017). "In addition, two novel gout-associated genes, HNF4G and SLC17A4, were found to affect the risk of gout in our study." (PMID 28252667, 2017). "All the urate transporter-coding genes, ABCG2, SLC2A9, SLC17A1 and SLC17A4, showed association with both the serum urate concentration and progression from hyperuricemia to gout and could affect the risk of gout." (PMID 28252667, 2017). "In addition, to avoid the heterogeneity of gender, logistic regression adjusted for gender was performed to confirm the association for HNF4G and SLC17A4, and the results also showed that those genes influence the risk of gout (PFDR = 8.92E-05 and 0.040, respectively)." (PMID 28252667, 2017). "In conclusion, this study systematically revealed the genetic effects on the pathogenesis of gout from elevated serum urate and identified two novel gout-associated genes (HNF4G and SLC17A4)." (PMID 28252667, 2017). "All candidate genes, except for SLC17A4, showed at least one significant difference in relative expression with a P value less than 0.05, indicating that the loci identified above might influence the risk of hyperuricemia and gout through changing the relative expression levels." (PMID 28252667, 2017). "ABCG2 and a novel gene, SLC17A4, contributed to the development of gout from hyperuricemia (OR = 1.56, PFDR = 3.68E-09; OR = 1.27, PFDR = 0.013, respectively)." (PMID 28252667, 2017). "In this study, we systematically analyzed the genetic variants influencing the progression from elevated serum urate to gout and identified 2 novel gout-associated genes (HNF4G and SLC17A4), using genetic analysis and mRNA expression analysis." (PMID 28252667, 2017). "For instance, the polymorphism of SLC17A4 has been associated with gout in Chinese patients but not in New Zealanders." (PMID 39518863, 2024). "In addition, five genes (PKD2, SLC2A9, SLC17A1, SLC17A4 and SLC17A2) were determined to influence the risk of gout (all PFDR < 0.05)." (PMID 29497127, 2018). "Furthermore, two novel gout-associated genes (HNF4G and SLC17A4) were identified." (PMID 28252667, 2017). "Six genes (A1CF, ABCG2, SLC2A9, TRIM46, SLC17A1 and SLC17A4) exhibited effects on the development of gout from hyperuricemia in males (all P < 0.05), but none of them exhibited such effects in females (all P > 0.05)." (PMID 28252667, 2017). "Because SLC17A4 did not affect the concentration of serum urate (PFDR = 0.108), the combined sample of HUA patients and healthy controls was treated as a larger sample control for the further analysis of gout." (PMID 28252667, 2017).
hyperuricemia (3 papers, 2017 to 2024). An abnormally high level of uric acid. "We speculate that Patient 7 should have some mutation in intestinal transporter (SLC17A4 or other), which caused hyperuricemia without change of FEUA." (PMID 38222853, 2024).
atherosclerosis (1 paper, 2017). A disease characterized by the build-up of fatty material and calcium deposition in the arterial wall resulting in partial or complete occlusion of the arterial lumen.
gestational diabetes (1 paper, 2022). Carbohydrate intolerance first diagnosed during pregnancy. "Related findings include differential methylation in cord blood in genes ATP5A1, MFAP4, PRKCH, SLC17A4 related to Gestational Diabetes (GDM); and hypermethylation of the LEP gene promoter associated with maternal obesity on the fetal side of the placenta." (PMID 35749371, 2022).
tumor (3 papers, 2018 to 2023). "Further in vitro functional experiments were performed using PCa cells to validate the association between the expression of hub gene SLC17A4 which is one of the model component genes and tumor progression." (PMID 36325340, 2022). "Some of these selected genes, such as CHRM4 and SLC17A4, involve in small molecule transport, tumour signal transduction and organism metabolism balance." (PMID 30514856, 2018). "Based on the cox analysis, we suggested that SLC17A4 might be an oncogene for the 3 evaluated types of tumor." (PMID 36325340, 2022). "The correlation between the expression of SLC17A4 and prognosis was evaluated in 33 tumor types." (PMID 36325340, 2022).
cancer (2 papers, 2021 to 2024). A tumor composed of atypical neoplastic, often pleomorphic cells that invade other tissues. "The roles of SLC39A5, UGT2A3 and SLC17A4 are relatively undescribed in cancer." (PMID 39556603, 2024).
SLC17A4 also shares sentences with these, for which no sentence is quoted: prostate carcinoma (2 papers); chronic rhinosinusitis (1); colon cancer (1); lupus (1); maturity onset diabetes (1); metabolic syndrome (1).